NEIL3 (nei like DNA glycosylase 3)
Diseases named in the same sentence as NEIL3 in open-access papers (continued):
Sharing a sentence is not in itself a finding about the gene and the disease.
tumor (continued). "Strikingly, the tumor volume of the NEIL3 upregulation group shrank faster than that of the control group." (PMID 34591415, 2021). "We also investigated the relationship between NEIL3 expression and tumor-infiltrating immune cells using Immune Cell Abundance Identifier (ImmuCellAI) and Tumor Immune Estimation Resource (TIMER)." (PMID 33879165, 2021). "The results revealed that NEIL3 overexpression was closely associated with advanced TNM stage (p < 0.05) and larger tumor size (p < 0.05)." (PMID 33879165, 2021). "Increased NEIL3 expression was related to advanced stage, larger tumor size and poor overall survival (p < 0.001) in three LUAD cohorts." (PMID 33879165, 2021). "We therefore investigated the expression of NEIL3 in several tumor types and their normal counterparts by using qPCR arrays containing cDNA from diseased and normal tissues." (PMID 19426544, 2009). "EXO1 and NEIL3, are both involved in DNA damage response and replication fork progression under oncogenic stress, suggesting their role in promoting genomic instability during tumor progression." (PMID 41402347, 2025). "Nei endonuclease VIII-like 3 (NEIL3), a DNA glycosylase crucial for repairing oxidative DNA damage and crosslinks, is highly expressed in multiple cancers (e.g., lung, kidney, liver) and promotes tumor progression." (PMID 41050691, 2025). "NEIL3 knockdown resulted in a significant reduction in both tumor volume and weight." (PMID 39910812, 2025). "In vivo, NEIL3 knockdown reduced tumor size and weight via WNT pathway modulation." (PMID 39910812, 2025). "Together, our findings have highlighted that NEIL3 may be a promising indicator for tumor immunotherapy and chemotherapy." (PMID 36612106, 2022). "Our research demonstrated that NEIL3 may be an indicator for both prognosis prediction and drug stratification, and it highlights the promising effect of NEIL3 in tumor therapy, which provides a foundation for future studies." (PMID 36612106, 2022). "In this study, we demonstrated that NEIL3 may be a promising indicator for tumor prognosis, immunotherapy, and chemotherapy." (PMID 36612106, 2022). "Previous high-throughput single nucleotide polymorphism array (SNP) analysis showed a high frequency of heterozygous loss of NEIL3 in HCC, suggesting that NEIL3 may rely on its DNA properties to act as a potential tumor suppressor gene in HCC." (PMID 36497204, 2022). "The molecular mechanism underlying NEIL3 gene and tumor microenvironment is still not known, which is our limitation and next crucial research question." (PMID 33879165, 2021). "The tumor NEIL3 level could serve as a promising prognostic indicator for OS and DFS rates in HCC patients after curative hepatectomy." (PMID 34659404, 2021). "Multivariate analysis and the prognostic nomograms revealed that tumor NEIL3 level may serve as a promising prognostic indicator for OS and DFS in HCC patients." (PMID 34659404, 2021). "Moreover, univariate and multivariate analyses demonstrated that tumor NEIL3 serves as an independent prognostic factor for OS and DFS, and the nomogram further validated the prognostic value." (PMID 34659404, 2021). "These variations, including those in GZMB, CXCL11, and NEIL3 suggest that the differences between patients from both races could be related to their immune response at the tumor niche." (PMID 32983990, 2020). "Human NEIL3 is expressed in the thymus, testes, and at high levels in tumor tissues." (PMID 29348879, 2017). "Finally, tumor tissues were shown to express higher amounts of NEIL3 compared to their normal counterparts, except for testis and pancreas." (PMID 19426544, 2009). "We have also looked at the expression of NEIL3 in several normal and tumor tissues." (PMID 19426544, 2009). "Furthermore, in NEIL3 knockout GBM cell lines, we observed the G2/M phase cell cycle arrest and a significant increase with replication-associated DSB; radiation treatment based on NEIL3 knockout further increased the mortality of tumor cells." (PMID 36497204, 2022).
tumor (continued). "In addition, NEIL3 seems to be upregulated in tumor tissues compared to normal tissues." (PMID 19426544, 2009). "We first assessed NEIL3 and TOP2A expression levels in an EC cell line and a non-tumor human esophageal epithelial cell line using qPCR." (PMID 39910812, 2025). "Among these genes, CDC25C, NEIL3, H2AFX, NBN, XRCC5 and RAD1 were all validated to be upregulated in NSCLC tumor tissues." (PMID 36408135, 2022). "Combined with the IHC-scores of our 406 patients cohort, NEIL3 expression was up-regulated in LUAD tissues and correlated with clinicopathological characteristics, especially advanced TNM stage and large tumor size." (PMID 33879165, 2021). "Compared with normal tissues, the expression levels of BEX1 in tumor tissues were significantly different, while the GCLM, G6PC, NEIL3 and NT5DC2 protein bands were unclear, which may be related to their low expression levels." (PMID 37745297, 2023). "To further explore the specific cellular expression patterns of these genes in HCC, we conducted scRNA-seq data to identify the distribution of G6PC, GCLM NEIL3 and NT5DC2 in different cell subclusters in HCC tissues including HCC tumor cells and non-tumor cells." (PMID 37745297, 2023). "Taken together, these studies indicated that with upregulated NEIL3 expression, RCC and HCC may activate the tumor-suppressive function of the infiltrated immunocytes through cell interplay in TME, despite having substantial immune components." (PMID 36612106, 2022). "These factors were then selected for DFS multivariate analysis, which revealed that NEIL3 expression (HR 1.947; 95% CI 1.233–3.074; P=0.004), TNM stage (HR 3.131; 95% CI 1.165–8.416; P=0.024), and tumor differentiation (HR 1.691; 95% CI 1.089–2.625; P=0.019) were significant factors of DFS." (PMID 34659404, 2021). "IHC showed that the NEIL3 protein level was remarkably upregulated in tumor tissues compared with nontumor tissues (fold change = 1.24; P < 0.001)." (PMID 34659404, 2021). "The histopathological scores revealed that NEIL3 protein expression was remarkably upregulated in tumor tissues compared with nontumor tissues (P < 0.001)." (PMID 34659404, 2021). "During the 20 days of tumor formation, we did not observe a difference in tumor volume between the control and NEIL3-overexpressing groups." (PMID 34591415, 2021). "Similarly, for patients with poor tumor differentiation, high NEIL3 expression indicated worse OS (P=0.003) and DFS (P < 0.001) compared with the patients with low NEIL3 expression." (PMID 34659404, 2021). "However, there was no remarkable difference between well tumor differentiation patients with high and low NEIL3 expression in OS (P=0.168) and DFS (P=0.044)." (PMID 34659404, 2021). "NEIL3, a DNA glycosylase of the BER pathway, repairs telomere oxidative damage and protects telomere integrity in cells with a high proliferative capacity during the S phase, which may explain the advanced Tumor stage in NEIL3 overexpressing patients." (PMID 33879165, 2021).
neurodegenerative disease (2 papers, 2022 to 2023). A disorder of the central nervous system characterized by gradual and progressive loss of neural tissue and neurologic function. "Other studies have also shown an important role of NEIL3 in fetal neurogenesis, as well as maintenance of adult neurogenesis in the hippocampus, thus implicating associations with neurodegenerative disease." (PMID 37337823, 2023).
neurological diseases (1 paper, 2022). "In addition, we also discuss the link between NEIL3 and the progression of cardiovascular and neurological diseases." (PMID 36497204, 2022).
NEIL3 also shares sentences with these, for which no sentence is quoted: liver cancer (3 papers); colon adenocarcinoma (2); rectal adenocarcinoma (2); triple-negative breast carcinoma (2); bladder urothelial carcinoma (1); cardiovascular disease (1); cholangiocarcinoma (1); cognitive decline (1); COVID-19 (1); differentiated thyroid carcinoma (1); gastric cancer (1); head and neck cancer (1); heart failure (1); immune dysfunction (1); neuroblastoma (1); neuropathy (1); Onset (1); Parkinson disease (1); primary immunodeficiency (1); sarcoma (1); scrapie (1); thyroid cancer (1); uterine corpus endometrial carcinoma (1).